EPCAM (epithelial cell adhesion molecule)
Diseases named in the same sentence as EPCAM in open-access papers (continued):
Sharing a sentence is not in itself a finding about the gene and the disease.
cancer (continued). "More recently, a bispecific EpCAM/CD3-antibody, antibody–drug conjugates (ADCs), and an antibody–cytokine fusion protein (termed immunocytokine) have emerged as promising EpCAM-targeting approaches for cancer treatment." (PMID 39595576, 2024). "Next, the immunofluorescent staining results of frozen section further demonstrated the presence of T cells in pLCOs, in contact with surrounding EpCAM expressing cancer cells." (PMID 38896792, 2024). "The development of diverse agents ranging from mAbs and immunotoxins to CAR-T cells and pharmacological inhibitors reflects the concerted efforts to exploit EpCAM’s significance as a contributor to stemness across multiple cancers." (PMID 38612911, 2024). "Expression microarray analysis revealed a set of 468 upregulated genes and 225 downregulated genes in EpCAM+ plastic cancer cells compared with full epithelial cancer cells." (PMID 39075581, 2024). "EpCAM has emerged as a promising target in cancer diagnosis and treatment, including as a cell surface marker to isolate CTCs and exosomes and to design CAR-T cell therapy." (PMID 38791091, 2024). "To address these, we firstly used microfluidic chips to detect the broad-spectrum of triple target combination biomarkers in CTCs of 10 types of cancer patients, including EpCAM, EGFR and Her2." (PMID 38720360, 2024). "EpCAM is a widely used cancer marker that is considered to be a highly effective antigen for detecting CTCs." (PMID 38746681, 2024). "The text describes the necessary processes for adding the immuno-affinity feature to hemodialyzer cartridges in order to capture CTCs that are positive for EpCAM, which accounts for approximately 80% of cancer cell types." (PMID 38746681, 2024). "The observation of EpCAM-mediated resistance to radiotherapy and chemotherapy suggests the potential of targeted EpCAM immunotherapy in cancer treatment." (PMID 38791091, 2024). "The amount of EpCAM-positive EVs (also CD81-positive) increased from 18% to 29% as the cancer progressed from Stage II to III." (PMID 39513819, 2024). "Previous studies have reported that epithelial cell adhesion molecule (EpCAM) promotes cancer cell self-renewal and bone metastasis." (PMID 39154024, 2024). "At present, EpCAM CAR-T cells are in the developmental stages for cancer therapy, with their potential application in HCC remaining unexplored." (PMID 39569202, 2024). "However, increased EpCAM expression has also been linked to improved patient survival in some cancers, including renal clear cell carcinoma and thyroid carcinoma, indicating its role as a cancer promoter or suppressor may be cancer-type specific." (PMID 38612911, 2024). "These cells did not self-colonize but created a pre-metastatic niche for a distinct population—the R-CSCs (reawakening cancer stem cells)—as evidenced by our bone marrow localization of EpCAM+ cells." (PMID 39963656, 2024). "Generally, EpCAM is ubiquitously expressed in cancer tissues of epithelial origin while showing low levels or even being absent in lymphomas, melanomas, and other tumors derived from mesenchymal or neural tissues." (PMID 38791091, 2024). "EPCAM is widely expressed in various malignant tumours, especially in digestive system tumour cells." (PMID 39183260, 2024). "To investigate the possible plastic nature of these cancer cell populations, we isolated α6-integrin+EpCAM+ cancer cells from WD-SCCs and MD/PD-SCCs, and α6-integrin+EpCAM− cancer cells from MD/PD-SCCs, and stably transduced them with GFP." (PMID 38914547, 2024). "It is found that the deficiency of FUT8 can down-regulate the stemness of cancer cells and result in the decrease of the expression of corresponding biomarkers, such as CD133, EpCAM, and c-Met." (PMID 38277230, 2024). "We generated WD-SCCs composed mainly of epithelial α6-integrin+EpCAM+ cancer cells from a putative epithelial-like CSC." (PMID 39075581, 2024).
cancer (continued). "We found that the amount of the EpCAM-positive EVs (also CD81-positive) or the CD24-positive EVs increased as the cancer progressed from Stage II to III." (PMID 39513819, 2024). "Our findings suggest that the BMP9-ID1 pathway fosters cancer stem cell characteristics in EpCAM-positive HCC cells by triggering the Wnt/β-catenin signaling pathway." (PMID 38256056, 2024). "EpCAM overexpression has been found to inhibit ERK activity in various cancer cell lines, while ERK is also capable of directly and indirectly suppressing EpCAM transcription." (PMID 38791091, 2024). "Although originally identified in colorectal adenocarcinoma, strong overexpression of EpCAM has been described in virtually all cancer types, such as breast, lung, bladder, prostate, esophageal, gastric, and pancreatic cancer." (PMID 37642704, 2024). "Captured CTCs will then be used to profile expression of cancer-specific membrane proteins such as EpCAM, cytokeratin (CK), vimentin, and CD133, where the latter two markers used to identify mesenchymal and stem cells phenotypes." (PMID 38811455, 2024). "Given the hybrid E/M phenotype exhibited by mouse cSCC plastic cancer cells, we evaluated their presence in different cSCC stages by analyzing the co-expression of epithelial EpCAM and mesenchymal Vimentin (Vim) markers in immunofluorescence (IF) assays." (PMID 39075581, 2024). "The significant association of high EpCAM levels with positive HPV status argues for a dependence of the EpCAM function and expression on the status of specific molecular pathways in cancer cells." (PMID 38786342, 2024). "Variability in EpCAM expression among cancer cells can significantly impact the capture effectiveness of immunoaffinity-based CTC platforms." (PMID 39492906, 2024). "A CAR-EpCAM T-cells clinical trial (NCT03013712) is enrolling patients with EpCAM-positive cancers to evaluate the safety and efficacy of this therapy." (PMID 39776907, 2024). "The serial engraftment of these WD-SCCs into new immunodeficient mice gave rise to MD/PD-SCCs formed of epithelial α6-integrin+EpCAM+ and mesenchymal α6-integrin+EpCAM− cancer cells." (PMID 39075581, 2024). "EpCAM positive HCC cells possess cancer stem cell (CSC) traits, including the capacity for self-renewal, differentiation, tumorigenesis, and chemotherapy resistance." (PMID 39199591, 2024). "In carcinoma cells, EpCAM takes part in cell adhesion, proliferation, migration, stemness, and epithelial-to-mesenchymal transition (EMT), showing its multifunctional transmembrane protein role." (PMID 39000215, 2024). "Epithelial Cell Adhesion Molecule (EpCAM), a transmembrane protein located on the cell surface, has traditionally served as a primary indicator for carcinomas and is commonly employed in cancer diagnostics." (PMID 39569202, 2024). "The authors further conjugated the AuNCs with an antibody against the epithelial cell adhesion molecule (CD326), a well-known marker for various human carcinomas." (PMID 39376728, 2024). "Although immunological approaches seem to be efficient, several studies demonstrated that CTCs of carcinoma origin have a heterogeneous expression of EpCAM and/or CK markers especially when they are in epithelial to mesenchymal transition (EMT) status." (PMID 38951573, 2024). "EpCAM is an antigen expressed in most normal epithelial cells, numerous stem and progenitor-type cells, and most carcinomas, and is highly overexpressed in cancer-initiating cell types." (PMID 39000215, 2024). "The EpCAM (CD326), a glycoprotein around 40 kDa, is a potential therapeutic target of cancers as this molecule is commonly expressed in the carcinoma of the colon, ovary, breast and prostate." (PMID 39472273, 2024).
cancer (continued). "Many technologies exist to isolate CTCs from patients’ blood samples, mostly based on microfluidic systems or by sorting them according to their surface antigens, notably EpCAM, and/or cytokeratins for carcinoma." (PMID 38951573, 2024). "The epithelial cell adhesion molecule (EpCAM), frequently overexpressed in a variety of carcinomas, serves as the target for immunotherapies." (PMID 39595576, 2024). "EpCAM is known to influence the growth, survival, and metastasis of cancer cells via its downstream effectors." (PMID 37543570, 2023). "The researchers demonstrated a successful capture of EpCAM-positive cancer cell lines, including MCF-7 breast cancer, SW480 colon cancer, and PC3 prostate cancer, with an efficiency exceeding 90%." (PMID 37754116, 2023). "The epithelial cell adhesion molecule (EpCAM) is found to be expressed on CSC across various cancer types." (PMID 38455361, 2023). "A good example is the TEPP bifunctional aptamer that from one end targets transferrin receptor (TfR) located on BBB ECs, and from the other end targets epithelial cell adhesion molecule (EpCAM) located on cancer cells within the brain." (PMID 37686652, 2023). "This remarkable activity of tetravalent bsAb CD73xEpCAM is most likely attributable to its enhanced avidity for binding to EpCAM exposed on the cancer cell surface and the concurrent blocking of the CD73 activity." (PMID 37509310, 2023). "The proposed electrochemical biosensor used two surface proteins (CD63 and EpCAM) as detection markers to distinguish four different types of cancer cells (4T1, Hela, HepG2, and A549)." (PMID 37050576, 2023). "The detection of CTCs is usually dependent on molecular markers, with adhesion molecules of epithelial cells (EpCAM) being the most widely used, although molecular markers vary between different types of cancer." (PMID 37753527, 2023). "Expression of the CD326 gene and protein (EPCAM), a representative surface marker of cancer stemness, was reduced, and it was found through flow cytometry that CD326 positive cells were decreased by LOXL2." (PMID 37737908, 2023). "For example, epithelial cell adhesion molecule (EpCAM) represents a common cancer biomarker that is used for immunomagnetic enrichment of cancer cell–derived EVs; it is only expressed in fewer than 50% of cancerous EVs." (PMID 37058564, 2023). "Unfortunately, to date no unique marker has been developed to effectively quantify circulating cancer cells and, despite the fact that EpCAM is still considered a valuable tool, its limitations should be taken into account." (PMID 37373781, 2023). "It knocks down EpCAM (epithelial cell adhesion molecule), which is overexpressed in malignant tumors." (PMID 37685710, 2023). "Additional palmitoylated proteins in cancer are Integrins, WNTs (Wnt1, 2B), cell adhesion molecules (EpCAM, MCAM), claudin 3, caveolin-1, Rab7a, estrogen receptors (ER α and β), Fas, IFNGR1, FLT3-ITD, LAT2, YKT6, VAMP3, GP130, Smad3, and GLUT1." (PMID 36671802, 2023). "Conversely, cancer cells, defined by EpCAM expression, scarcely expressed IR ligands, with the exception of HLA-DR and of a minority of samples highly positive for PD-L2." (PMID 37868997, 2023). "Increasing evidence has shown EpCAM to be a CSC marker for numerous cancers, such as breast cancer, CRC166, HCC188,191, NPC176, and pancreatic cancer." (PMID 38164743, 2023). "Where available from the Charles River Cancer Model Database, EpCAM expression was shown in a heat map." (PMID 37190054, 2023). "After attaching to the EpCAM-expressing surface of cancer cells, MOC31PE kills cells by deactivating crucial cellular functions." (PMID 37190310, 2023). "EpCAM is recognized as one of the cell surface markers used for the identification and isolation of CSCs from various cancer types." (PMID 36899854, 2023). "As previously elucidated, the majority of cancers originate from epithelial cells, making EpCAM the most commonly used marker for CTCs." (PMID 37998325, 2023).
cancer (continued). "We observed a significant reduction of EpCAM-positive cells in both cancer patients and contaminated blood, which was comparable to the negative control after leucodepletion." (PMID 37373781, 2023). "EpCAM is expressed in both healthy and cancer tissues; however, it is usually overexpressed in cancerous tumors derived from epithelial tissues." (PMID 37175871, 2023). "Altogether, data prove the AND-gate feature of the Dual-RevCAR system targeting CEA and EpCAM on double positive cancer cells." (PMID 38169746, 2023). "We observed potent and specific elimination of various EpCAM-positive carcinoma cell lines as well as primary patient-derived cancer cells in the presence of HLA-B*07:02-restricted anti-CMV CD8pos T cells." (PMID 37568582, 2023). "EpCAM is silenced in mesenchymal cancer cells; this suggests that cancers that retain their epithelial features can also retain high levels of expression of the classical MHC I haplotypes." (PMID 38067396, 2023). "Catumaxomab is a trifunctional antibody intraperitoneal (IP) immunotherapy authorized in Europe that can be used to diminish malignant ascites by targeting EpCAM." (PMID 37190310, 2023). "Increased EpCAM expression in patients is correlated with poor prognosis and therapeutic refractoriness because EpCAM supports cancer growth and progression through modulation of cell proliferation, differentiation, migration, and invasion." (PMID 37303738, 2023). "We used mIHC to visually analyze GCPM cells at 15 h after treatment with PBS or CF33-hNIS-antiPDL1 for anti-PD-L1 scFv (green), EpCAM (brown for cancer cells), PD-L1 (purple), and Treg cells (yellow for FoxP3) expression." (PMID 37762490, 2023). "We conducted an oncology protein array to measure 84 major cancer-related proteins in both A549 cells and A549 EVs and found that EpCAM, EGFR, Dkk-1, Galectine-3, Endostatin, E-Cadherin, FGF basic, Vimentin, and progranulin are the top nine hits." (PMID 36834913, 2023). "The EPCAMhigh (or EPCAMpositive) cell fraction within the liver has been described as a candidate progenitor cell population, and EPCAM has also been reported to be a cancer stem cell (CSC) biomarker for hepatocellular carcinoma." (PMID 36674577, 2023). "Heatmaps were utilized to compare the expression profiles of imputed and ground truth data for immune (CD45+), epithelial/cancer (EpCAM), and stromal (CD10+ and CD34+) subsets." (PMID 37509650, 2023). "Anti-EpCAM Ec1–LoPE DARPin–toxin fusion demonstrated efficacy in several cancer models, both alone and in combination with other targeting agents." (PMID 36769161, 2023). "Dissociating exosomes from OC serum has been reported using an antibody-functionalized microfluidic framework to identify biomarkers present in cancer exosome membranes (e.g., EpCAM, CD9)." (PMID 37082219, 2023). "One of the attractive targets for immunotherapy is EpCAM (CD326), a 39–40 kDa human cell surface glycoprotein, which is highly expressed in many cancer cells such as ovarian, breast, colorectal, prostate, lung, pancreatic, and others." (PMID 37345198, 2023). "The effectiveness of this approach was assessed by isolating CTCs from prostate (n = 17) and pancreatic (n = 5) cancer patients using EpCAM alone, vimentin alone, and both antibodies together." (PMID 37345161, 2023).
cancer (continued). "In vitro BC studies reported that the overexpression of EpCAM promotes proliferation, invasion, and metastasis in cancer cells." (PMID 36899854, 2023). "The epithelial cell adhesion molecule (EpCAM) is effective in a broad range of cancer immunotherapies involving this stem cell antigen." (PMID 37366915, 2023). "The expression of EpCAM varies with different cancer types and is mainly applied to cancers such as breast and prostate which strongly express EpCAM." (PMID 36774504, 2023). "All anti-CEA and anti-EpCAM RevTMs were validated and the simultaneous targeting of CEA+ and EpCAM+ cancer cells redirected specific in vitro and in vivo killing by Dual-RevCAR T-cells." (PMID 38169746, 2023). "Expression and stabilization of Snail protein is involved in EMT and cancer metastasis, so we wanted to determine if EpCAM regulates Snail expression." (PMID 37543570, 2023). "Overexpression of EpCAM on CTCs makes it a promising marker for cancer diagnosis as well as monitoring and isolation of CTCs." (PMID 37303738, 2023). "Antibodies to EpCAM have been developed for cancer therapy, either as a native monoclonal agent, anti-EpCAM toxin-conjugated antibody, or IL2-conjugated antibody that exhibit promising clinical activity." (PMID 37303738, 2023). "In combination these findings strongly argue against a major cancer driving role of TROP2/EpCAM activation (or inactivation) in muscle-invasive urothelial carcinoma." (PMID 38282671, 2023). "In one series of assays, EpCAM-positive cancer cells were treated with 3-17I-Saporin (biotinylated 3-171 mixed with Streptavidin-ZAP) and the photosensitizer TPCS2a (Amphinex), followed by light exposure." (PMID 36977072, 2023). "Our results show that anti-PD-L1 scFv (green) was expressed by CF33-hNIS-antiPDL1-infected ex vivo GCPM cells, and colocalized with EpCAM-positive cancer cells." (PMID 37762490, 2023). "LCSCs have various molecular markers, among which epithelial cell adhesion molecule (EpCAM) is a marker of cancer-initiating cells in the liver and other epithelial tissues." (PMID 37046749, 2023). "The anti-63B6 antibody was able to target mesenchymal-stem-cell-like cancer cells and intermediate cancer cells, a population that is often omitted in strictly anti-EpCAM selection, thus increasing capture efficiency." (PMID 37241658, 2023). "A clinical study (NCT00836654) was conducted in EpCAM+ cancer patients suffering from malignant ascites, demonstrating that catumaxomab treatment slowed deterioration in quality of life (QoL) for patients to achieve a prolonged survival period." (PMID 36910604, 2023). "For HCC model, markers including CK8, CK18, HepPar-1, Arg-1, AFP, HSP70, GPC3, CEA, CD24, CD133 and EpCAM can be used to identify cancer type and cancer progression." (PMID 37188191, 2023). "We humanized the AUA1 antibody and tested binding by FACS using the EpCAM-positive Lovo cancer cell line and the EpCAM knockout (KO) Lovo cell line generated with CRISPR/Cas-9." (PMID 37345198, 2023). "Microarray data from analysis of cancer cell lines revealed 121 genes, including EpCAM, closely correlated (R>0.6) to the bonafide epithelial marker E-cadherin." (PMID 37192201, 2023). "These include cancer stem cell (CSC) markers: (i) surface receptors, including EpCAM/CD326, CD44 variants, Notch-ligand Dll4, prominin/CD133, (ii) extracellular ligands, including Wnt, and (iii) functional enzymes (ALDH and MMPs)." (PMID 36671802, 2023).